XPO1 (exportin 1)
Diseases named in the same sentence as XPO1 in open-access papers (continued):
Sharing a sentence is not in itself a finding about the gene and the disease.
tumor (continued). "This was done to capture the modulatory effect of XPO1 inhibition on the localization and expression of key tumor suppressor proteins prior to apoptosis." (PMID 25057921, 2014). "A reduced level of XPO1 protein was also observed in tumor xenografts isolated from CBS-9106-treated mice." (PMID 25476752, 2014). "The effects of XPO1 inhibition on expression of these tumor suppressor proteins have been well-documented in a variety of human tumor cell lines treated with SINE compounds and this is likely a significant contributor to loss of cell viability." (PMID 25022346, 2014). "Cytoplasmic XPO1 protein expression was correlated with increased mitotic index, more aggressive tumor growth, advanced tumor stage, and poor OS." (PMID 25476752, 2014). "This indicates that XPO1 inhibition combined with T cell engagers may enhance anti-tumour immunity and this warrants further in vivo investigations." (PMID 40291981, 2025). "Pharmacologic inhibition of XPO1 with selective inhibitors such as selinexor disrupts multiple oncogenic pathways, restores tumor suppressor activity, modulates the tumor microenvironment, and enhances responses to standard therapies, including targeted agents and adoptive immunotherapies." (PMID 41440011, 2025). "Through similarity analysis and enrichment analysis, we observed that XPO1 could participate in multiple tumor progression signals in ccRCC, including E2F, PI3K-AKT, interferon-alpha, and TGF-beta signaling axes." (PMID 39882192, 2025). "Indeed, we found that XPO1 can exert a tumor‐promoting function by reducing the nuclear localization of RB1." (PMID 39888288, 2025). "The XPO1 blockade promoted the differentiation of MDSCs into T-cell-activating neutrophil-like cells, which enhanced the overall antitumor immune response and restrained tumor growth." (PMID 40565816, 2025). "Circ_0001017, produced from the backsplicing of exportin 1 (XPO1), acts as a tumor inhibitor." (PMID 40778324, 2025). "Additionally, XPO1 inhibition can impair the production of the immunosuppressive cytokine IL-10, potentially preventing the inhibition of an ongoing anti-tumour immune response." (PMID 40291981, 2025). "We observed that XPO1 expression levels were significantly upregulated in ccRCC tumor tissues." (PMID 39882192, 2025). "We showed that combining eIF4A inhibition with the FDA-approved XPO1 inhibitor selinexor resulted in a potent synergistic effect in cell culture and in profound tumor growth suppression and extended survival in both orthotopic and patient-derived xenograft models." (PMID 41279557, 2025). "Preclinical data in the current literature support the hypothesis that XPO1 inhibition may reprogram the tumor immune microenvironment, making it less tumor-permissive." (PMID 40004846, 2025). "The ROC curve showed that XPO1 in OSCC could be used to distinguish normal samples from tumor samples." (PMID 39177040, 2024). "Protein mislocalisation via XPO1 is a significant contributor to tumour drug resistance." (PMID 38783482, 2024). "The expression of XPO1 was compared between tumor and normal samples in the OSCC dataset of TCGA." (PMID 39177040, 2024). "Targeting XPO1 offers a promising therapeutic strategy by retaining multiple tumor suppressor proteins in the nucleus, preventing the translation of oncoproteins, inducing transient cell-cycle arrest, suppressing tumor growth, and promoting apoptosis." (PMID 38927948, 2024).
tumor (continued). "Accumulating evidence suggests that XPO1 may mediate drug resistance in multiple tumour types by promoting the nuclear export of multiple drug targets." (PMID 38783482, 2024). "However, we found that the relative fold change in XPO1 levels was significantly higher in tumor cell lines as compared to normal cell lines (P value 0.044)." (PMID 38589567, 2024). "Despite its recognised significance, the mechanism underlying the overexpression of XPO1 in numerous tumours has not been elucidated." (PMID 38783482, 2024). "In addition, a 2022 study found that an inhibitor of exportin 1 (XPO1), selinexor, synergized with chemotherapy to inhibit tumor growth in PDXs of chemoresistant relapse patients." (PMID 39456533, 2024). "The upregulation of XPO1 expression disrupts the balance of nucleoplasmic transport and leads to the mislocalisation of tumour suppressor proteins and oncoproteins, which consequently promotes tumour progression and potentially fosters therapeutic resistance." (PMID 38783482, 2024). "In our primary murine HCC model, XPO1 inhibition induced remarkable tumor regression." (PMID 38302473, 2024). "XPO1 mediates the nuclear export of several proteins, mainly tumor suppressors." (PMID 36200270, 2023). "The rationale for targeting XPO1 in MM reflects that in other tumour types." (PMID 37601856, 2023). "Considering the limited therapeutic opportunities for recurrent or metastatic SGT and the variety of cellular pathways in which XPO1 is involved, combination treatment strategies may be required to improve anti‐tumor responses." (PMID 37818869, 2023). "Additionally, relative to the sh-NC group, USP14 and XPO1 expressions in the tumor tissues were declined in the sh-USP14 group." (PMID 37082728, 2023). "However, therapeutic responses to XPO1 inhibitor monotherapy remain unsatisfactory, suggesting that combination treatments are necessary to improve the cytotoxic effects of XPO1 inhibitors against tumor cells." (PMID 37899423, 2023). "Inhibition of XPO1 thus impacts tumour cells via 3 core mechanisms: increasing nuclear levels and activation of TSPs; trapping oncoprotein mRNA in the nucleus, leading to reduced oncoprotein levels; and retaining activated glucocorticoid receptor (GR) in the nucleus." (PMID 37601856, 2023). "Exportin-1 (CRM1) is critical for CPC binding to centromeres when interacting with BIRC5, and thus, modulating the heterodimeric BIRC5/CRM1 complex, a number of pathogenic processes, including tumor cell proliferation, can be affected." (PMID 35053254, 2022). "It has been hypothesized that XPO1 exports particularly tumor suppressor proteins from the cell nucleus so that they cannot exert their tumor suppressive effects." (PMID 36230711, 2022). "The tumor selectivity of the Selinexor-mediated radiosensitization could, at least in part, be attributed to the overexpression of XPO1 in tumor cells." (PMID 35260696, 2022). "In the search for combination regimens able to increase the response to selinexor, we reasoned that a concomitant strategy for down-regulating survivin expression could have had a positive impact on the XPO1 inhibitor anti-tumor activity." (PMID 34072442, 2021). "In tumor cells, exportin-1-mediated nuclear export has been shown to be upregulated and may cause cytoplasmic mis-localization of tumor suppressors, drug resistance and augmented tumor growth." (PMID 34003336, 2021). "Moreover, analysis of tumor remnants showed that Selinexor disrupts the interaction between XPO1 and PAR-4, activated PAR-4 signaling, and reduces the proliferation of tumor cells." (PMID 34575598, 2021).
tumor (continued). "XPO1 transcript expression was quantified via qRT‐PCR in 21 primary canine OS tumours and XPO1 protein expression was assessed by Western blotting in eight primary canine OS tumours to determine if XPO1 represents a relative target for therapeutic intervention." (PMID 33438820, 2021). "One crucial lesson from the development of XPO1 inhibitors is that while irreversible inhibition by leptomycin B produced severe toxicity, development of inhibitors that allow physiological export had much less toxicity, but maintain efficacy in tumor cells." (PMID 32624581, 2020). "This study concludes that XPO1-mediated protein export is general and promiscuous and that the impaired export of tumor suppressors may be one of the multiple potential mechanisms of action for XPO1 inhibitors." (PMID 32487143, 2020). "Similar to what has been shown in targeted and immunotherapies, detailed tumor stratification based on genomic, pathohistological, and/or immunological characteristics can help delineate the specific subset of tumors responsive to XPO1 inhibitors." (PMID 32487143, 2020). "Here, we demonstrate that XPO1 inhibition in DHL tumor cells abrogates MYC protein expression." (PMID 31752970, 2019). "Because XPO1 exports multiple tumor suppressor proteins simultaneously from the nucleus, the inhibition of XPO1 may retain multiple tumor suppressors in the nucleus, resulting in the suppression of cell proliferation and induction of apoptosis in tumors." (PMID 31382411, 2019). "In such circumstances, the SINE treatment combined with miR-30 therapy could decrease the level of XPO1, leading to the synergistic inhibition of tumor growth." (PMID 31382411, 2019). "First, in our published analysis from publicly available tumor datasets and data from patient tumor samples mRNA and protein levels of XPO1 were higher in Luminal B subtype tumors, which are more likely to recur on endocrine treatments relative to Luminal A subtype." (PMID 30987380, 2019). "Moreover, suppression of XPO1 with selective inhibitors of nuclear export (SINEs) has been shown to downregulate MYC expression in several tumor types." (PMID 31752970, 2019). "The overexpression of XPO1 within the tumor cells may reflect its abundance and suggests a gain-of-function or oncogenic activity in line of further CRC pathogenesis." (PMID 31870117, 2019). "Because XPO1 exports multiple tumor suppressor proteins simultaneously from the nucleus, the inhibition of XPO1 may retain multiple tumor suppressors in the nucleus, resulting in the suppression of cell proliferation and the induction of apoptosis in tumors." (PMID 31382411, 2019). "Many tumor types overexpress XPO1 compared to normal tissue." (PMID 31569391, 2019). "Furthermore, we tested the expression levels of AR-v7 and XPO1 in tumor tissues from the patients with PCa." (PMID 30450161, 2018). "Tumor 3 represents tumors with strong XPO1 staining in most nuclei and cytoplasm." (PMID 30349650, 2018). "Working in this direction we demonstrated that XPO1 RNAi interference or chemical inhibition by XPO1 specific small molecule drugs could re-align tumor suppressive microRNAs leading to inhibition of pancreatic cellular growth." (PMID 29735942, 2018). "We found that the tumor tissues with high level of AR-v7 also expressed higher level of XPO1, suggesting that there could be a molecular interaction between XPO1 and AR splice variants." (PMID 30450161, 2018). "The effect of XPO1 inhibition in tumor growth was determined in vivo using a mouse xenograft model." (PMID 30115935, 2018). "Western blot analysis of lysates of tumor tissue showed that selinexor decreased the protein levels of XPO1 and cyclin B1 and increased the levels of p21 and cleaved caspase 3 in the mice receiving selinexor compared with tumors in mice treated with vehicle control." (PMID 27893412, 2017).
tumor (continued). "The clinical validation of the pharmacological inhibition of XPO1 was recently achieved with the development of the selective inhibitor of nuclear export compounds, displaying an interesting anti-tumor activity in patients with massive pre-treated hematological malignancies." (PMID 28196522, 2017). "XPO1 is overexpressed in tumor cells and high levels are correlated with poor prognosis." (PMID 29299164, 2017). "XPO1 overexpression positively correlated with a larger tumor size in ESCC." (PMID 28196522, 2017). "However, how XPO1 controls miRNA shuttling and subsequently increases miR-145 and other tumor suppressive miRNAs is still poorly understood." (PMID 29137251, 2017). "This is the first report that XPO1 inhibition can modulate a critical tumor suppressive miRNA (miR-145) that may control PDAC cell proliferation, invasiveness and metastasis." (PMID 29137251, 2017). "In this study, we are the first to report that XPO1 inhibition (by RNAi or selinexor) can up-regulate the expression of tumor suppressive miR-145 and, in turn, down-regulate the expression of its target pathways, leading to the inhibition of proliferation and migration of PDAC cells." (PMID 29137251, 2017). "In addition to the induction of miR-145 in PDAC cells, RNAi of XPO1 or selinexor treatment increased the expression of other tumor suppressive miRNAs including let-7d, miR-34c and miR-320, and decreased the expression of oncogenic miR-205." (PMID 29137251, 2017). "The same general principle may apply to XPO1 inhibition, where in a particular tumor cell context, cell survival is exquisitely dependent on the cytoplasmic localization (or reduced nuclear localization) of an XPO1 cargo." (PMID 26654943, 2016). "Our goal was to use this method to quantify XPO1 occupancy in patient tumor biopsies." (PMID 26654943, 2016). "Thus, XPO1 inhibition provides a novel and promising anticancer strategy able to prevent inactivation of tumor suppressors and the translation of several key mRNAs and proteins by preventing their export and restricting them to the nucleus." (PMID 27487856, 2016). "It is perhaps this aberrant order that is most vulnerable to XPO1 inhibition in tumor cells." (PMID 26991404, 2016). "The XPO1 occupancy assay could be used to determine direct inhibition of XPO1 in a specific tumor biopsies but only from intact and viable cells." (PMID 26654943, 2016). "XPO1/CRM1 has been reported to have an increased expression in several tumor types." (PMID 25948791, 2015). "Although cyclin D1 could be responsible for the anti-tumor effect of XPO1 inhibition, it is known that the overexpression of cyclin D1 itself is not sufficient for development of MCL." (PMID 26340096, 2015). "Interestingly, while there are six other known nuclear export proteins (XPO2-7), XPO1 is the sole nuclear exporter for the major tumor suppressor and growth promoting proteins." (PMID 25057921, 2014). "In addition, tumor size and presence of distant metastasis also correlated with increased levels of XPO1 protein." (PMID 25476752, 2014). "Because XPO1 inhibition impacts multiple anti-tumor and growth suppressive signaling pathways, it may impact PCa including those that have become androgen independent." (PMID 25284315, 2014). "The objective of our study was to test the hypothesis that XPO1 inhibition affects the metastatic potential of PCa cells using one model of intraprostatic tumor growth and two models of bone metastasis." (PMID 25284315, 2014). "From a clinical point of view, elevated expression of XPO1 is associated with increased tumor size and negative histological grade." (PMID 25476752, 2014). "Cellular component (CC) analysis highlighted the localization of XPO1 within the nucleus, cytoplasm, and extracellular exosome, while molecular function (MF) analysis identified its role in protein binding and RNA binding, further supporting its regulatory function in tumor progression." (PMID 40806458, 2025).
tumor (continued). "Selinexor selectively targets XPO1 and contributes to the intranuclear storage and activation of tumour suppressor proteins and other growth-regulating proteins, downregulates the levels of multiple oncogenic proteins in the cytoplasm and induces apoptosis of tumour cells." (PMID 40375183, 2025). "Notably, we identified XPO1+Epithelial within the tumor that may promote tumor progression and contribute to the regulation of the TME through cellular communication networks." (PMID 39712016, 2024). "Additionally, XPO1+Epithelial regulates endothelial cells via VEGFA-VEGFR1R2 and VEGFA-VEGFR1, which may be associated with promoting tumor vascular production." (PMID 39712016, 2024). "Furthermore, we found that inhibition of XPO1 significantly inhibited tumor cell proliferation." (PMID 36200270, 2023). "Inhibition of XPO1-mediated nuclear transport can prevent the excessive nuclear export of tumor-suppressor proteins, antiapoptotic proteins, and growth-regulator proteins and thereby maintain the effective concentration of such proteins in the nucleus and exert a tumor-suppressor effect." (PMID 36110547, 2022). "However, it remains unclear if this is a direct or indirect effect of XPO1 inhibition, and the role solute carries, or their substrates may have in selinexor-mediated anti-tumor effectiveness." (PMID 36059685, 2022). "Thus, high XPO1 activity favors tumor progression and therapeutic resistance." (PMID 31052304, 2019). "Therefore, the enforced expression of the miR-30 family could inhibit the expression of XPO1, resulting in the suppression of tumor growth in vitro and in vivo." (PMID 31382411, 2019). "Therefore, inhibition of NFκB by upregulating IκBα protein and subsequent creation of NFκB-IκBα complexes may be, at least in part, the mechanism behind proteasome inhibition and XPO1 inhibitor anti-tumor synergy." (PMID 27806331, 2016). "Therefore FAS/FASL system could be activated and FASL produced in the tumor microenvironment by pro-inflammatory and resident stromal cells could participate to the XPO-1 mediated cell death." (PMID 26620414, 2015). "Most importantly, the combination of two clinical drugs (CDK4/6 inhibitor Palbociclib and XPO1 inhibitor KPT‐330) effectively inhibited BLBC cell proliferation and tumor growth." (PMID 39888288, 2025). "Our combination approach ofco-targeting KRASG12D and XPO1 resulted in enhanced growth suppression of KRASG12D-mutantPDAC cells and cell-derived tumor xenografts." (PMID 41394580, 2025). "Tumor-derived intestinal three-dimensional cultures from the FAP mouse model, Apcmin/+, showed high dependency on XPO1 for survival and growth, whereas low doses of eltanexor had marginal effects on WT three-dimensional cultures." (PMID 40601866, 2025). "Consistently, a combination of XPO1 inhibitor KPT‐330 and CDK4/6 inhibitor Palbociclib effectively inhibited BLBC cell proliferation and tumor growth." (PMID 39888288, 2025). "XPO1 inhibition traps BCR–ABL in the nucleus, re-sensitizing leukemia cells to the BCR–ABL inhibitor imatinib and resulting in a substantial reduction in tumor cell proliferative potential with limited toxicity to normal myeloid precursors." (PMID 41440011, 2025). "Exportin 1 (also referred to as XPO1 or CRM1) is a nuclear receptor that is involved in the export of a wide range of proteins, including many tumor suppressors and oncoproteins as well as RNA species." (PMID 40001478, 2025). "Further analysis indicated that the expression of XPO1 and RCN2 was greater in tumor tissues with high Ki67 expression." (PMID 39712016, 2024). "Therefore, inhibition of XPO1 may constitute a new strategy for tumour therapy." (PMID 38783482, 2024).